ACOT7 (acyl-CoA thioesterase 7)
Diseases named in the same sentence as ACOT7 in open-access papers (continued):
Sharing a sentence is not in itself a finding about the gene and the disease.
cancer (13 papers, 2010 to 2026). A tumor composed of atypical neoplastic, often pleomorphic cells that invade other tissues. "ACOT7 plays a role in immune cell infiltration and is closely associated with the cancer immune microenvironment." (PMID 40823187, 2025). "Further enrichment analyses reveal that ACOT7 is involved in immune cells’ infiltration and is substantially related to the cancer–immune microenvironment." (PMID 36139682, 2022). "Collectively, ACOT7 is a prognostic biomarker in various cancers, especially in ACC, KIRP, LIHC, LUSC, and MESO." (PMID 36139682, 2022). "This is the first study regarding this topic, but on the other hand, the function of ACOT7 in more cancers needs to be further verified." (PMID 36139682, 2022). "It suggested that in most cancer types, except UCC, ACOT7 mRNA expression is significantly associated with TME pathways, especially with DNA damage, repair, and TME score A pathways." (PMID 36139682, 2022). "We successfully evaluated the role of ACOT7 from the pan-cancer perspective and further investigated the biological function of ACOT7 in LUAD." (PMID 36139682, 2022). "In the present study, ACOT7 expression negatively correlates with the DNA methylation level in 28 of 33 cancers, except OV, DLBC, LAML, GBM, and CHOL." (PMID 36139682, 2022). "Cancer tissues exhibited higher ACOT7 mRNA levels than normal tissues (P=0.0052; data are presented as mean±S.E.M)." (PMID 28518146, 2017). "In this study, for the first time, ACOT7 was shown to be responsive to genotoxic stresses such as ionizing radiation (IR) and the anti-cancer drug doxorubicin in time- and dose-dependent manners." (PMID 28518146, 2017). "We also analyzed gene expression data from the Cancer Genome Atlas and observed upregulated ACOT7 expression in carcinoma breast tissues compared with normal breast tissues." (PMID 28518146, 2017). "In our study, ACOT7 was aberrantly expressed in various cancers through TCGA and HPA databases." (PMID 36139682, 2022). "Moreover, according to ESTIMATE scores, ACOT7 was involved in immune cell infiltration in most cancers." (PMID 36139682, 2022). "High ACOT7 expression was significantly correlated with poorer prognoses of various cancers." (PMID 36139682, 2022). "In addition, ACOT7 expression was positively correlated with CNA in 25 of 33 cancers except CHOL, DLBC, LAML, PCPG, THYM, THCA, LGG, and KIRP." (PMID 36139682, 2022). "In these cancers, the trend of ACOT7 gene alteration was consistent with its mRNA expression level." (PMID 36139682, 2022). "To date, studies investigating the role of ACOT7 in cancers are seldom." (PMID 36139682, 2022). "The correlation between long-term survival and ACOT7 mRNA expression in pan-cancer was explored." (PMID 36139682, 2022). "To determine whether or not ACOT7 expression was altered after treatment with the anti-cancer drug Doxo, we measured ACOT7 mRNA and protein levels in Doxo-treated MCF7 cells." (PMID 28518146, 2017). "Therefore, we aimed to explore the expression level, prognostic significance, molecular function, signaling pathways, and immune infiltration pattern of ACOT7 in 33 types of cancer via systematic bioinformatics analysis and perform functional experimental validation in LUAD." (PMID 36139682, 2022). "ACOT7 might alter the metabolism of cancer cells by regulating TME-related pathways." (PMID 36139682, 2022). "Furthermore, we demonstrated the synergistic effect of ACOT7 depletion and treatment with either IR or Doxo on cancer cell proliferation, suggesting ACOT7 might be a novel target for anti-cancer therapy." (PMID 28518146, 2017). "Taken together, our study first unveiled a complicated role of ACOT7-aberrant expression in clinical prognosis, immune cell infiltration, TMB, or MSI in pan-cancer." (PMID 36139682, 2022). "Research on the functions of ACOT7 are seldom, and comprehensive pan-cancer analysis is lacking." (PMID 36139682, 2022).
ACOT7 also shares sentences with these, for which no sentence is quoted: Alzheimer disease (2 papers); diabetes type 1 (2); gastric cancer (2); infection (2); ovarian carcinoma (2); allergic respiratory disease (1); atherosclerosis (1); autoimmune disease (1); bacteremia (1); bacterial infection (1); breast invasive ductal carcinoma (1); cardiovascular diseases (1); cervical cancer (1); dementia (1); eosinophilia (1); ependymoma (1); Fanconi anemia (1); Huntington disease (1); liver disease (1); liver fibrosis (1); neurodegenerative disease (1); osteomyelitis (1); ovarian epithelial tumor (1); Pan (1); Parkinson disease (1); pneumonia (1); posterior fossa ependymoma (1); schizophrenia (1); thymoma (1).